PGAP2 (post-GPI attachment to proteins 2)
Description:
Involved in the fatty acid remodeling steps of GPI-anchor maturation where the unsaturated acyl chain at sn-2 of inositol phosphate is replaced by a saturated stearoyl chain. May catalyze the second step of the fatty acid remodeling, by reacylating a lyso-GPI intermediate at sn-2 of inositol phosphate by a saturated chain (By similarity). The fatty acid remodeling steps is critical for the integration of GPI-APs into lipid rafts.
Synonyms: FRAG1; CWH43-N; HPMRS3; MRT17; MRT21
Tractability: Antibody: UniProt predicts a signal peptide or a membrane-spanning region. PROTAC: ubiquitination databases record sites on it.
Gene: Protein-coding gene on chromosome 11 (3,797,724 to 3,826,371, forward strand). Ensembl gene ENSG00000148985.
Subcellular location: Golgi apparatus membrane
Subcellular location (Human Protein Atlas): Microtubules
Gene Ontology:
Molecular function: protein binding
Biological process: GPI anchor biosynthetic process
Cellular component: Golgi membrane; endoplasmic reticulum membrane; membrane
Genetic constraint (gnomAD): Loss-of-function variants: 21 observed, 34.72 expected, observed/expected ratio (o/e) 0.6, 90% interval 0.43 to 0.87. The upper end of that interval is the gene's LOEUF score, 0.87, which puts it in group 3 of 6, group 1 being the genes least tolerant of losing a copy. Missense variants: 345 observed, 438.19 expected, observed/expected ratio (o/e) 0.79, 90% interval 0.72 to 0.86. Synonymous variants: 161 observed, 180.7 expected, observed/expected ratio (o/e) 0.89, 90% interval 0.78 to 1.01.
Homologues: Orthologues: chimpanzee PGAP2 (99% identical), macaque PGAP2 (98% identical), rat Pgap2 (93% identical), dog PGAP2 (79% identical), mouse Pgap2 (76% identical), pig PGAP2 (75% identical), rabbit PGAP2 (68% identical), guinea pig PGAP2 (67% identical), rat AABR07038703.1 (56% identical), tropical clawed frog pgap2 (45% identical), zebrafish pgap2 (42% identical), Drosophila melanogaster PGAP2 (36% identical), and 9 more.
Diseases named in the same sentence as PGAP2 in open-access papers:
PGAP2 is named in the same sentence as 23 diseases in open-access papers, as found by Europe PMC text mining. Sharing a sentence is not in itself a finding about the gene and the disease. The quoted sentences say what the papers report.
hyperphosphatasia (13 papers, 2016 to 2025). "Genetic analyses revealed homozygous and novel compound heterozygous missense variants in PGAP2 in four affected individuals, confirming the molecular diagnosis of hyperphosphatasia with impaired intellectual development syndrome 3 (HPMRS3)." (PMID 40225942, 2024). "Biallelic pathogenic variants in PGAP2 have been associated with hyperphosphatasia with impaired intellectual development syndrome 3 (HPMRS3, MIM 614207)." (PMID 40225942, 2024). "Compound heterozygous PGAP2 mutations were identified in a female patient presenting with developmental delay (DD), ID, speech delay, epilepsy, and hyperphosphatasia." (PMID 40225942, 2024). "Mutations in GPI pathway proteins have been linked to a wide variety of rare genetic disorders, while mutations in PGAP2 specifically have been shown to cause to intellectual disability, hyperphosphatasia, and petit mal seizures." (PMID 36519529, 2022). "To date, 7 mutations in PGAP2 gene have been identified as a cause of hyperphosphatasia with mental retardation syndrome (HPMRS)." (PMID 29119105, 2017). "Altogether, our data demonstrate that the autosomal recessive syndrome of hyperphosphatasia with mental retardation in this family is caused by a rare homozygous variant in PGAP2 which was previously reported in dbSNP database and that a mild phenotype could be observed in heterozygous carriers." (PMID 29119105, 2017). "For example, following detection of compound heterozygous VUS in PGAP2, we confirmed hyperphosphatasia through clinical biochemical testing." (PMID 37471090, 2023). "This is exemplified in the PEDIA cohort by Hyperphosphatasia with Mental Retardation Syndrome (HPMRS), where the least frequently mutated gene, PGAP2, shows the lowest performance." (PMID 31164752, 2019). "Mutations in six different genes (PIGV, PIGY, PIGO, PGAP2, PIGW, and PGAP3) involved in GPI-anchor biosynthesis have been shown to cause hyperphosphatasia with mental retardation syndrome (HPMRS)." (PMID 29119105, 2017). "Recently, mutations have been identified in six genes (PIGA, PIGY, PIGO, PGAP2, PIGW and PGAP3) encoding proteins in the Glycosyl phosphatidylinositol(GPI)-anchor-synthesis pathway in individuals with hyperphosphatasia with impaired intellectual development syndrome(HPMRS)." (PMID 39687712, 2024). "In conclusion, this case report represents the first documentation of PGAP2-related Hyperphosphatasia with impaired intellectual development syndrome in the Asian population, thereby expanding our understanding of the genetic and phenotypic spectrum of the disease." (PMID 39687712, 2024). "To date, mutations in six genes (PIGV, PIGY, PIGO, PGAP2, PIGW, and PGAP3) have been shown to cause hyperphosphatasia with mental retardation syndrome (HPMRS) in an autosomal recessive mode of inheritance (no autosomal dominant mutations have been reported thus far)." (PMID 29119105, 2017).
Intellectual disability (6 papers, 2016 to 2023). "The critical role of Pgap2 in the regulation of the central nervous system functioning and structural remodelling is corroborated by the fact that mutations in this gene produce an autosomal recessive syndrome characterised by intellectual disability and mental retardation." (PMID 37185241, 2023).
Mabry syndrome (4 papers, 2015 to 2024). "As a result of identifying the biallelic PGAP2 variants in the Mabry syndrome index patients, we gained insight into the phenotype that became the basis of all GPIBD studies." (PMID 38790248, 2024). "Hyperphosphatasia Mental Retardation syndrome (HPMRS, MIM 239300, MIM 214749, and MIM 614207), also known as Mabry syndrome, was found to be associated with PIGV (MIM 610274), PIGO (MIM 614730),PGAP2 (MIM 615187) and PGAP3 (MIM 611801) mutations." (PMID 25885527, 2015).
microcephaly (3 papers, 2017 to 2024). A congenital or acquired developmental disorder in which the circumference of the head is smaller than normal for the person's age and sex. "While most features of this syndrome are shared between individuals with mutations in the PGAP2 Frag1 domain, some phenotypic variability exists, with various degrees of microcephaly, seizures, and mild dysmorphic features." (PMID 29119105, 2017).
cleft lip (2 papers, 2019 to 2024). Congenital defect in the upper lip where the maxillary prominence fails to merge with the merged medial nasal prominences. "Hypomorphic Pgap2 mutant mice, generated via ENU mutagenesis, exhibit the Clpex phenotype (cleft lip, cleft palate, edema, and exencephaly) due to apoptosis of neural crest cells (NCCs) and the cranial neuroepithelium." (PMID 40225942, 2024).
epilepsy (2 papers, 2024 to 2026). A brain disorder characterized by episodes of abnormally increased neuronal discharge resulting in transient episodes of sensory or motor neurological dysfunction, or psychic dysfunction. "ES and epilepsy gene panel analyses identified three missense variants in PGAP2 in four affected individuals in both families." (PMID 40225942, 2024).
Anxiety (1 paper, 2023). Intense feelings of nervousness, tension, or panic often arise in response to interpersonal stresses. "Subsequently, elevated-plus maze testing revealed decreased anxiety-like behaviour in animals with reduced Pgap2 expression as evidenced by a ~40% increase in the number of entries into the open arms of the maze, likewise observed in animals overexpressing the miR-483-5p." (PMID 37185241, 2023). "Similarly to miR-483-5p overexpression, Pgap2-targeted shRNA prevented the development of anxiety-like behaviour following stress." (PMID 37185241, 2023).
brachydactyly (1 paper, 2024). A disease characterized by the presence of brachydactyly, including syndromic and non-syndromic forms. "The four patients in our study displayed common phenotypic features, such as brachydactyly, camptodactyly, and syndactyly, which have not been previously documented in individuals with PGAP2 variants." (PMID 40225942, 2024).
cleft palate (1 paper, 2019). Cleft palate is a fissure type embryopathy that affects the soft and hard palate to varying degrees. "As Pgap2 was highly expressed in the epithelium and epithelial barrier defects are a known cause of cleft palate, we next sought to determine whether the epidermis was compromised in the Clpex mutant." (PMID 31232685, 2019).
deficiencies (1 paper, 2020). "Hyperphosphatemia is a characteristic symptom of some GPI deficiencies, including PIGO, PIGW, PGAP2, etc.." (PMID 32220244, 2020).
megacolon (1 paper, 2018). "To date, megacolon has only been found to be associated with PIGV, PIGO, and PGAP2 mutations." (PMID 29310717, 2018).
neurodevelopmental disorder (2 papers, 2024). A behavioral and cognitive disorder with onset during the developmental period that involves impaired or aberrant development of intellectual, motor, or social functions. "In this study, we reported two patients with PGAP2 variants related neurodevelopmental disorders from Asian population." (PMID 39687712, 2024). "PGAP2 stands out among these genes due to its association with an expanded clinical spectrum of neurodevelopmental disorder (NDD) phenotypes with biallelic pathogenic variants." (PMID 40225942, 2024).
PGAP2 also shares sentences with these, for which no sentence is quoted: genetic diseases (3 papers); developmental delay (2); Camptodactyly (1); cancer (1); COVID-19 (1); Hirschsprung disease (1); hyperphosphatemia (1); mitochondrial disease (1); neurological disorder (1); Seizure (1); syndactyly (1).